BCHE (butyrylcholinesterase)
Diseases named in the same sentence as BCHE in open-access papers (continued):
Sharing a sentence is not in itself a finding about the gene and the disease.
Alzheimer disease (continued). "Inhibition of acetylcholinesterase (AChE) and butyrylcholinesterase (BChE) has great potential in the treatment of Alzheimer’s disease and special focus has been directed to these targets." (PMID 33352776, 2020). "The synthesized compounds were evaluated against acetylcholinesterase (AChE) and butyrylcholinesterase (BChE), because these enzymes play a crucial role in the treatment of Alzheimer’s disease." (PMID 32046020, 2020). "Butyrylcholinesterase (BChE)—another member of the cholinesterase family—is also postulated to upsurge in the late stages of Alzheimer’s disease and to accumulate in the amyloid plaques (Aβ)." (PMID 32586060, 2020). "Tacrine (TC) (9-amino-1,2,3,4-tetrahydroacridine), a non-selective, reversible cholinesterase inhibitor, affecting acetylcholinesterase and butyrylcholinesterase, was launched as the first drug to alleviate the symptoms of Alzheimer’s disease." (PMID 32547358, 2020). "Brain butyrylcholinesterase (BChE) is an attractive target for drugs designed for the treatment of Alzheimer’s disease (AD) in its advanced stages." (PMID 31914836, 2020). "Physostigmine has patents related to inhibition of acetylcholinesterase and the treatment of AD (EP0296560), enhancing memory (US5177101, US2007197663), inhibition of butyrylcholinesterase and treatment of Alzheimer’s disease as well as dementia (EP0949920)." (PMID 31937840, 2020). "(2014) also investigated the effect of R. graveolens on the inhibition of acetylcholinesterase (AChE) and butyrylcholinesterase (BuChE), which are considered as promising strategies in the treatment of Alzheimer’s disease (AD)." (PMID 32432948, 2020). "The development of novel inhibitors of acetylcholinesterase (AChE) and butyrylcholinesterase (BuChE) represents a viable approach to alleviate Alzheimer’s disease." (PMID 31694272, 2019). "Reducing and capping agent; acetylcholinesterase and Butyrylcholinesterase inhibitory activities; excellent free radical scavenging and metal chelating activity, suitable for Alzheimer’s disease therapy." (PMID 31795265, 2019). "The higher hydrolytic activity of AChE is partly compensated by the increased or constant level of BChE during the course of Alzheimer’s disease." (PMID 31671776, 2019). "A novelty in terms of evaluation of hop cone biofunctionality is the determination of a marker related to the activity of AChE and BChE inhibitors used in the treatment of neurodegenerative diseases, especially in Alzheimer’s disease." (PMID 31248112, 2019). "As there are increased levels and activity of butyrylcholiesterase (BChE) in the late stage of Alzheimer’s disease (AD), development of selective BChE inhibitors is of vital importance." (PMID 31757047, 2019). "All the compounds were found to be potent inhibitors of both acetylcholinesterase (AChE) and butyrylcholinesterase (BChE), two enzymes responsible for the hydrolysis of the neurotransmitter acetylcholine in Alzheimer’s disease patient brains." (PMID 30544832, 2018). "Rivastigmine (Riv) is a potent and selective cholinesterase (acetylcholinesterase, AChE and butyrylcholinesterase, BuChE) inhibitor developed for the treatment of Alzheimer’s disease (AD)." (PMID 30557385, 2018). "The inhibitions of AChE and BChE activities have been established as an effective strategy for treatment of Alzheimer's disease (Howes, Perry, & Houghton, 2003)." (PMID 30349669, 2018). "Butyrylcholinesterase (BChE) in normal brain and in Alzheimer’s disease (AD) regulates cognitive and behavioural functions." (PMID 29358722, 2018). "Recent studies on the impact of brain BChE on the symptoms and progression of cognitive impairments promoted BChE as an important target in future Alzheimer disease pharmacotherapy." (PMID 30289893, 2018). "One last concern for risks in treatments based on prolonged elevation of BChE levels, is the nearly ubiquitous findings of BChE deposits in the senile plaques of brains in patients who die with Alzheimer’s disease." (PMID 29535625, 2018).
Alzheimer disease (continued). "New hybrid analogs were evaluated against acetylcholinesterase (AChE) and butyrylcholinesterase (BuChE) in order to know their potential for the prevention of Alzheimer's disease (AD)." (PMID 29632858, 2018). "We investigated the anti-Alzheimer disease (anti-AD) potential of these coumarins by assessing their ability to inhibit acetylcholinesterase (AChE), butyrylcholinesterase (BChE), and β-site amyloid precursor protein (APP) cleaving enzyme 1 (BACE1)." (PMID 28946641, 2017). "The major role of AChE is to catalyse the hydrolysis of acetylcholine (ACh) in cholinergic synapses, while BChE can hydrolyse ACh as well as other esters; nevertheless, it seems its concentration in brain is especially important at Alzheimer’s disease (AD)." (PMID 29135926, 2017). "Among them, inhibition of acetylcholinesterase, butyrylcholinesterase, and prolyl oligopeptidase can be beneficial targets in the treatment of Alzheimer’s disease." (PMID 28708094, 2017). "Chief among those issues is to determine the impact of BChE, in its catalytically active form or disabled by eliminating its active-site serine, on the onset and progression of Alzheimer’s disease." (PMID 28698452, 2017). "Ethanolic extracts from leaves and flowers displayed the highest inhibitory activity against acetylcholinesterase and butyrylcholinesterase, showing potential properties against Alzheimer's disease." (PMID 27314007, 2016). "Rivastigmine is a reversible and competitive inhibitor of acetylcholinesterase and butyrylcholinesterase used for symptomatic treatment of Alzheimer dementia and Parkinson's disease." (PMID 27073702, 2016). "Previous studies have demonstrated that berberine possesses multiple activities in Alzheimer's disease therapy, including antioxidant activity, AChE and BChE inhibitory activity, MAO inhibitory activity, and reducing Aβ level and lowering cholesterol." (PMID 27769241, 2016). "β-Carboline bivalent derivatives that are known inhibitors for acetylcholinesterase (AChE) and butyrylcholinesterase (BChE) were developed for imaging of cholinesterase in Alzheimer’s disease." (PMID 26942181, 2016). "The enhanced activity of AChE and BChE is detrimental to patients suffering from Alzheimer's disease." (PMID 27486373, 2015). "Although the etiology of Alzheimer's disease (AD) is not fully understood, nevertheless, inhibition of acetylcholinesterase (AChE) and butyrylcholinesterase (BChE) activity has been accepted as an effective treatment/management strategy against mild AD." (PMID 25506036, 2014). "Utilizing of the dual Acetylcholinesterase/Butyrylcholinesterase inhibitors has gained more interest to treat the Alzheimer’s disease." (PMID 23445881, 2013). "Hologram QSAR models were developed for a series of 36 inhibitors (29 training set and seven test set compounds) of acetyl/butyrylcholinesterase (AChE/BChE) enzymes, an attractive molecular target for Alzheimer’s disease (AD) treatment." (PMID 22878227, 2012). "Inhibition of acetylcholinesterase has successfully been used as a drug target to treat Alzheimer's disease but drug resistance shown by butyrylcholinesterase remains a matter of concern in treating Alzheimer's disease." (PMID 20550720, 2010). "Butyrylcholinesterase was studied in relation to both type 2 diabetes mellitus and Alzheimer's disease in different ethnic groups." (PMID 17096857, 2006). "Alzheimer's disease (AD) remains a significant global health challenge, highlighting the need for novel dual inhibitors targeting acetylcholinesterase (AChE) and butyrylcholinesterase (BChE)." (PMID 41976156, 2026). "This study reports the design and synthesis of a novel series of cinnamic acid-based analogs bearing an N-benzyl pyridinium moiety against Alzheimer's disease (AD), aiming at dual inhibition of acetylcholinesterase (AChE) and butyrylcholinesterase (BChE), alongside neuroprotective effects." (PMID 41704453, 2026).
Alzheimer disease (continued). "Cholinesterase (ChE) enzyme family, consisting of acetylcholinesterase (AChE) and butyrylcholinesterase (BChE), play a significant role in the pathology of Alzheimer’s disease (AD) due to their involvement in acetylcholine (ACh) breakdown, a crucial neurotransmitter for memory and learning." (PMID 41596508, 2026). "Furthermore, HM is considered a potential candidate for the treatment of Alzheimer's disease as it inhibits acetylcholinesterase (AChE) and butyrylcholinesterase (BChE) activity." (PMID 40496271, 2025). "A novel series of 4‐(diethylamino)salicylaldehyde‐based thiosemicarbazone derivatives 5(a–u) were synthesized and screened for their potential against Alzheimer's disease, by testing for their inhibitory effects against cholinesterases (AChE and BChE) and monoaminoxidase A (MAO‐A) and B (MAO‐A)." (PMID 40685770, 2025). "In addition, acetylcholinesterase (AChE) and butyrylcholinesterase (BChE) are other critical enzymes in health care, and their inhibitors are used in the clinical management of Alzheimer’s disease." (PMID 40649366, 2025). "Also, the study demonstrated the effectiveness of the different fractions of Fagonia arabica L. in inhibiting the butyrylcholinesterase enzyme, which is a key contributor to the progression of Alzheimer’s disease." (PMID 39939326, 2025). "This manuscript reports the synthesis and characterization of 19 novel heterostilbene carbamates, designed as selective butyrylcholinesterase (BChE) inhibitors with potential applications in the treatment of neurodegenerative disorders, particularly Alzheimer’s disease." (PMID 40563465, 2025). "Notably, 5,7,4′-trimethoxyflavone and 5,7-dimethoxyflavone have demonstrated potent inhibitory effects on acetylcholinesterase (AChE) and butyrylcholinesterase (BChE), suggesting their therapeutic potential in treating Alzheimer’s disease." (PMID 41375950, 2025). "In addition, BChE plays a role in neurodegenerative diseases such as Alzheimer’s disease (AD) by influencing cholinergic neurotransmission through the hydrolysis of acetylcholine." (PMID 40116876, 2025). "While AChE is the primary enzyme responsible for acetylcholine breakdown in the central nervous system under normal conditions, BChE becomes upregulated in several neurodegenerative conditions, including Alzheimer’s disease (AD), where it is often found in higher concentrations in the brain." (PMID 40563465, 2025). "Therefore, therapeutic approaches for Alzheimer’s disease (AD) were established in the form of inhibitors of AChE (acetylcholinesterase) and BChE (butyrylcholinesterase)." (PMID 40461519, 2025). "Moreover, Diels−Alder-type adducts have been characterized as multitargeted agents for Alzheimer’s disease; mulberrofuran G and albanol B showed strong AChE- and BChE-inhibitory activities." (PMID 38257228, 2024). "Some of the plant extracts obtained in our study, especially the ethyl acetate and the butanolic ones, exhibited potent antioxidant, AChE, and BChE inhibitory activities, and anti-neurotoxic potential, properties that may be useful against Alzheimer’s disease." (PMID 39684612, 2024). "The inhibition of AChE and BChE by taxifolin is likely due to its ability to bind to their active sites, which could have therapeutic implications for the treatment of Alzheimer’s disease and other neurodegenerative disorders." (PMID 38338420, 2024). "The extracts also showed inhibitory activity on AChE and BChE enzymes at levels comparable with inhibitors obtained from other natural sources, exhibiting potential for use in treatments aiming to fight and/or protect against Alzheimer’s disease." (PMID 38254569, 2024). "Similarly, Donepezil and Rivastigmine are potent, selective, non-competitive, and rapidly reversible inhibitors of both acetylcholinesterase and butyrylcholinesterase, and are approved for the treatment of Alzheimer’s disease." (PMID 39458923, 2024).
Alzheimer disease (continued). "Studies have shown that the expression level and activity of the butyrylcholinesterase enzyme increases significantly in the late stages of Alzheimer’s disease, so butyrylcholinesterase can be considered as a promising therapeutic target for potential Alzheimer’s treatments." (PMID 38971857, 2024). "Inhibition of AChE and BChE may be helpful in the treatment of Alzheimer’s disease; similarly, Parkinson’s disease can also be fought by inhibiting the action of the tyrosinase enzyme." (PMID 38671929, 2024). "The extracts exhibited strong inhibitory activity against acetylcholinesterase, butyrylcholinesterase, α-amylase, α-glucosidase, and tyrosinase, indicating potential therapeutic applications for global health issues such as skin hyperpigmentation, Alzheimer’s disease, and diabetes mellitus." (PMID 39410171, 2024). "Additionally, its potential in mitigating neurodegenerative processes is evaluated through enzyme inhibition assays, particularly focusing on butyrylcholinesterase (BChE), a key enzyme involved in Alzheimer’s disease." (PMID 39512543, 2024). "BChE is predominantly expressed in white matter and glial cells (specifically astrocytes), while AChE is localized in neuronal areas that are crucial for cognition and behavior, regions that undergo functional impairment in Alzheimer’s disease." (PMID 39596378, 2024). "We considered both acetylcholinesterase (AChE) and butyrylcholinesterase (BChE) due to their physiological roles as therapeutic targets involved in the symptoms of Alzheimer’s disease, in the treatment of which the currently available drugs are AChE inhibitors." (PMID 38667790, 2024). "These are required for correct brain function, and it is thought that dysregulation of ACheE and BChE may lead to the progression of Alzheimer’s disease." (PMID 36675191, 2023). "In addition, allicin acts as a potent inhibitor of cholinesterase and butyrylcholinesterase, suggesting its anti-Alzheimer’s disease potential." (PMID 36765652, 2023). "The current study suggested polyacetylene glycosides as promising leads for the dual inhibition of 5-LOX and BchE enzymes, which could be applied for the prevention and treatment of neuroinflammatory disorders, such as Alzheimer’s disease." (PMID 37110760, 2023). "When combining the inhibitory data from these three main enzymes that control Alzheimer’s disease occurrence, DL and DM had more than 90% inhibition against AChE and BChE and more than 60% inhibition against BACE-1 as two potential herbal extracts for reducing the risk of Alzheimer’s disease." (PMID 38066118, 2023). "Although a clear physiological function has not been identified for it, abnormal BChE serum levels are found in patients with conditions such as neurological disorders (especially Alzheimer's disease), obesity, type 2 diabetes and elevated cardiovascular risk." (PMID 36004682, 2023). "Two hypotheses of the mechanisms of Alzheimer’s disease occurrence involve (i) termination of neurotransmitters by two cholinergic enzymes, AChE and BChE, and (ii) β-amyloid formation by BACE-1." (PMID 38066118, 2023). "In Alzheimer’s disease, BChE expression and function are increased in certain brain regions." (PMID 36769002, 2023). "These compounds could be used to discover novel specific BChE inhibitors for the treatment of Alzheimer’s disease." (PMID 38202655, 2023). "The most promising enzymes, whose inhibition is considered helpful in the pathology of Alzheimer’s Disease (AD), may be acetylcholinesterase (AChE) and butyrylcholinesterase (BChE)." (PMID 37242476, 2023). "The dual inhibition of acetylcholinesterase and butyrylcholinesterase is beneficial for Alzheimer’s disease patients, especially since butyrylcholinesterase replaces acetylcholinesterase in the acetyl choline catabolism in advanced Alzheimer’s disease patients." (PMID 35630702, 2022). "BChE plays a key role in the progression of Alzheimer’s disease (AD), a neurodegenerative disorder." (PMID 35337102, 2022).
Alzheimer disease (continued). "Alzheimer’s Disease (AD) is characterized by a progressive cholinergic neurotransmission imbalance, with a decrease of acetylcholinesterase (AChE) activity followed by a significant increase of butyrylcholinesterase (BChE) in the later AD stages." (PMID 36678552, 2022). "Therefore, restoring acetylcholine by inhibiting AChE and BChE with phytoconstituents from plants is the modern method for treating Alzheimer's disease and neurodegenerative illnesses." (PMID 36573158, 2022). "The main function of AChE is the rapid hydrolysis of the neurotransmitter acetylcholine (ACh) on the cholinergic synapses associated with Alzheimer’s disease (AD), whereas butyrylcholinesterase (BChE) is not correlated with any physiological abnormalities." (PMID 35630752, 2022). "To summarize, in subjects with Alzheimer’s disease, caffeic acid decreases oxidative stress and improves cognitive functions, probably by inhibiting NF-κB and GSK3β signaling and acetylcholinesterase and butyrylcholinesterase activity." (PMID 36614030, 2022). "Furthermore, researchers have discovered that berberine inhibits the four major enzymes involved in the pathogenesis of Alzheimer's disease: acetylcholinesterase, butyrylcholinesterase, monoamine oxidase A, and monoamine oxidase B." (PMID 35586776, 2022). "Recently, it has been reported that antioxidants inhibit enzymes such as butyrylcholinesterase (BChE), acetylcholinesterase (AChE), α-amylase, carbonic anhydrase, and α-glycosidase, which are associated with diseases such as type 2-DM (T2DM), Alzheimer’s disease (AD), and glaucoma." (PMID 36144638, 2022). "Additionally, it exhibits beneficial effects in the nervous system, including ameliorating Alzheimer’s disease by inhibiting BChE activity and alleviating depression by acting on 5-HT1A receptors." (PMID 33967765, 2021). "As an inhibitor of cholinesterase and (AChE) and butyrylcholinesterase (BuChE) it can be applied to manage the Alzheimer’s disease, helps to maintain the balance of neurotransmitters in case of autism spectrum disorder (ASD) and attention deficit hyperactive syndrome (ADHD)." (PMID 35052591, 2021). "Finally, the development of new acetylcholinesterase (AChE) and butyrylcholinesterase (BuChE) inhibitors represents a viable approach to alleviate Alzheimer’s disease." (PMID 34071744, 2021). "With respect to the modulation of enzymes targeted in the management of Alzheimer’s disease (acetylcholinesterase, butyrylcholinesterase) and type 2 diabetes mellitus (amylase, glucosidase), the current data suggest moderate inhibitory effects of Piper spices against the investigated enzymes." (PMID 34679776, 2021). "It has been previously reported that chrysin exhibited antioxidant activities by quenching 2,2-diphenyl-1-picrylhydrazyl (DPPH) radicals, and inhibited acetylcholinesterase (AChE) and butyrylcholinesterase (BChE), the enzymes involved in Alzheimer’s disease (AD) pathogenesis and cognitive decline." (PMID 34441689, 2021). "Levels of AChE and BChE in the brain are increased in Alzheimer’s disease." (PMID 31752064, 2020). "The cholinergic deficit in Alzheimer’s disease is a well-known phenomenon, and the restoration of cholinergic function by inhibiting the (acetylcholinesterase) AChE and butyrylcholinesterase (BChE) activity is an effective treatment strategy for Alzheimer’s disease." (PMID 33374338, 2020). "It has previously been reported that the flavonol quercetin and some polyphenol-rich extracts are able to inhibit the enzymes anticholinesterase (AChE) and butyrylcholinesterase (BChE), demonstrating thereby neuroprotective effect against pathologies such as Alzheimer’s disease." (PMID 32580356, 2020). "Species from the Petasites genus are traditionally used for the treatment of migraine, which suggested their potential for the treatment of other neurological disorders including Alzheimer’s disease e.g., acting as acetylcholinesterase and butyrylcholinesterase inhibitors." (PMID 32486467, 2020).